PIEZO1 (piezo type mechanosensitive ion channel component 1 (Er blood group))
Diseases named in the same sentence as PIEZO1 in open-access papers (continued):
Sharing a sentence is not in itself a finding about the gene and the disease.
Hepatic steatosis (3 papers, 2019 to 2025). Steatosis is a term used to denote lipid accumulation within hepatocytes. "Association between intestinal PIEZO1 and liver steatosis was evaluated by detecting PIEZO1 expression in distal ileum mucosa from individuals with or without fatty liver." (PMID 39781454, 2025). "Although the role and mechanism of FGF15/19 played in liver steatosis was still ambiguous, we confirmed that FGF15 reduction mediated the amelioration of liver steatosis caused by PIEZO1 deficiency by applying FGF19 supplementary experiment in HFD-fed Piezo1ΔIEC mice." (PMID 39781454, 2025). "After supplementary of exogenous FGF19, the effect of improving liver steatosis brought by PIEZO1 deletion was blocked." (PMID 39781454, 2025). "Altogether, IEC PIEZO1 represents a promising target for therapy of hepatic steatosis via the gut-liver axis." (PMID 39781454, 2025). "The adipose-Piezo1−/− mice also developed hepatic steatosis with elevated expression of fatty acid synthesis genes." (PMID 31263454, 2019). "In the present study, IEC-specific deficiency of PIEZO1 alleviated HFD-induced liver steatosis, without change on glucose and energy metabolism, providing us with a new target for MASLD treatment." (PMID 39781454, 2025). "We investigated whether activating Piezo1 could alleviate diet-induced hepatic steatosis in obese mice." (PMID 40446026, 2025). "The effect of IEC PIEZO1 deficiency on liver steatosis was liver-targeted to a great extent, because there was no significant change in whole-body metabolism and fat distribution." (PMID 39781454, 2025). "Compared to control persons, lower PIEZO1 expression was observed in humans with fatty liver." (PMID 39781454, 2025). "However, intestinal PIEZO1 deficiency did not affect hepatic steatosis under a normal chow diet." (PMID 39781454, 2025). "In summary, our research suggests that manipulating the mechanosensitive ion channel Piezo1 in intestinal L cells can influence the release of GLP-1, with potential implications for the progression of fatty liver disease." (PMID 40446026, 2025). "IEC PIEZO1 deletion significantly alleviated liver steatosis, without change on glucose tolerance and energy expenditure." (PMID 39781454, 2025).
hereditary anemia (3 papers, 2021 to 2025). "Individuals carrying mutations in the PIEZO1 gene exhibit hematological aberrations and hereditary anemia, supporting the importance of Piezo1 in RBC homeostasis." (PMID 40483587, 2025). "The PIEZO1/spectrin relation is emphasized by the recent study showing a coinheritance of PIEZO1 and spectrin mutations in a cohort of 155 patients with clinical suspicion of hereditary anemia." (PMID 34737711, 2021).
hereditary spherocytosis (3 papers, 2015 to 2023). Hereditary spherocytosis is a congenital hemolytic anemia with a wide clinical spectrum (from symptom-free carriers to severe hemolysis) characterized by anemia, variable jaundice, splenomegaly and cholelithiasis. "It is not clear why red cells adopt a stomatocytic shape in conjunction with increased cation leak, and the spherocytes seen in one family (GLD4) are likely to also be due to the PIEZO1 mutation, and suggest that some cases of spherocytosis could be caused by mutations in this gene." (PMID 26333996, 2015). "Accordingly, upon decreases in cytoskeleton membrane occupancy and stiffness in erythrocytes from patients with hereditary spherocytosis, Piezo1 fluorescence was increased." (PMID 38254651, 2023). "In support of this possibility, we have shown a negative correlation between membrane stiffness at low load and Piezo1 MFI in RBCs from patients with spherocytosis." (PMID 38254651, 2023). "Moreover, the interplay between Piezo1 clusters, cytoskeleton and membrane stiffness was evidenced through the use of RBCs from patients with hereditary spherocytosis." (PMID 38254651, 2023). "In support of this hypothesis, our unpublished data on patients with spherocytosis indicate alteration in PI contents and metabolism that could partly support the impairment of Piezo1 in this disease." (PMID 38254651, 2023). "By comparison with data obtained from different healthy donors, the Piezo1 MFI was increased, although non-significantly, in three out of the four spherocytosis patients and inversely correlated with the septin-to-ankyrin ratio and the spectrin membrane occupancy." (PMID 38254651, 2023).
hypertrophic cardiomyopathy (3 papers, 2021 to 2025). A condition in which the myocardium is hypertrophied without an obvious cause. "Doxorubicin-induced dilated cardiomyopathy induced an increase in Piezo1 expression in CM, and clinical data revealed increased Piezo1 expression in heart biopsies from patients with hypertrophic cardiomyopathy." (PMID 33922466, 2021).
Intellectual disability (3 papers, 2015 to 2022). "On the other hand, our patient showed peculiar characteristics: the hydrocele never observed in the other PIEZO1 loss-of-function patients, and the absence of facial swelling, lymphangiectasia, and intellectual disability." (PMID 30930797, 2019).
metabolic syndrome (3 papers, 2024 to 2025). A cluster of metabolic risk factors for CARDIOVASCULAR DISEASES and TYPE 2 DIABETES MELLITUS. "PIEZO1 variants in people were associated with hepatobiliary disease and dyslipidemia." (PMID 39331703, 2024). "Therefore, people who carry a gain-of-function mutation may have increased risk of dyslipidemia and benefit most should PIEZO1 inhibitors become available as a therapeutic strategy." (PMID 39331703, 2024).
muscle atrophy (3 papers, 2022 to 2026). The loss of muscle tissue due to inactivity or disease. "Collectively, this work establishes that the Piezo1/Osteocalcin/Irisin axis mediates mechanical unloading-induced muscle atrophy and highlights this axis as a promising therapeutic target for disuse-induced muscle atrophy." (PMID 41995090, 2026). "In conclusion, by generating new mouse models with inducible Piezo1 expression, we have shown that acute overexpression of Piezo1 in skeletal muscle attenuates immobility-induced muscle atrophy, suggesting the therapeutic potential of Piezo1 activation for this condition." (PMID 40533105, 2025). "Moreover, the contribution of the Piezo1/KLF15/IL-6 axis to immobilization-induced muscle atrophy identified in mice was validated with the use of biopsy samples of patients with cast fixation–induced skeletal muscle atrophy." (PMID 35290243, 2022).
Osteopenia (3 papers, 2024 to 2026). Osteopenia is a term to define bone density that is not normal but also not as low as osteoporosis. "In mammals, Piezo1 is essential for bone homeostasis; Piezo1-deficient mice display osteopenia and increased bone fragility, underscoring its importance in skeleton development." (PMID 41303344, 2025). "Systemic administration of the Piezo1 agonist Yoda1 attenuated HLU-induced osteopenia and improved bone formation capacity." (PMID 41362723, 2026). "In this study, we found that systemic infusion of MSC-derived exogenous apoVs could eliminate senescent cells via restoring Piezo1 expression and calcium influx, and eventually eliminate senescent cells and rescue osteopenia in mechanical unloading mice." (PMID 39239523, 2024).
Pleural effusion (3 papers, 2020 to 2023). The presence of an excessive amount of fluid in the pleural cavity. "This study found that endothelial-specific deletion of Piezo1 caused the mice to develop pleural effusion and die within 2 weeks after birth, which was associated with an impairment in valve leaflet protrusion into the lumen leading to drastically fewer valves." (PMID 32824219, 2020). "In the lymphatic vasculature, deletion of the Piezo1 gene in mice leads to a severe reduction in the number of valves and pleural effusion." (PMID 32824219, 2020). "Piezo type mechanosensitive ion channel component 1 (PIEZO1), a cation channel activated by mechanical forces such as fluid shear stress or membrane stretch, is a causative gene associated with congenital lymphedema with pleural effusion." (PMID 36439271, 2022).
psoriasis (3 papers, 2022 to 2025). An autoimmune condition characterized by red, well-delineated plaques with silvery scales that are usually on the extensor surfaces and scalp. "In summary, these data demonstrate the pivotal role of PIEZO1 in psoriasis by modulating the transcription of genes associated with inflammatory responses, highlighting its function as a positive regulator of the NF-kB signaling pathway." (PMID 40495117, 2025). "Our study delves into the intricate biological mechanisms underlying psoriasis, highlighting the prominent role of PIEZO1—a mechanosensitive ion channel—in the etiology of this disease." (PMID 40495117, 2025). "PIEZO1, a mechanically activated ion channel, has been implicated in various cellular processes, but its role in psoriasis pathogenesis remains unclear." (PMID 40495117, 2025). "The role of PIEZO1 in the development of psoriasis-like skin inflammation was elucidated using an IMQ-induced mouse model." (PMID 40495117, 2025). "The results of our study support previous findings that demonstrate increased expression of PIEZO1 in the epidermis of individuals with psoriasis, consistent with numerous recent investigations examining PIEZO1 in other inflammatory conditions." (PMID 40495117, 2025). "Understanding the molecular effects of PIEZO1 on keratinocyte action and immune signaling is imperative for devising targeted psoriasis therapies." (PMID 40495117, 2025). "The beneficial effects of PIEZO1 silencing in psoriasis are attributed to the inhibition of the NF-κB signaling pathway." (PMID 40495117, 2025). "Our research suggests that PIEZO1 is not only a crucial component for maintaining keratinocyte homeostasis but also a promising therapeutic target for treating psoriasis." (PMID 40495117, 2025). "Our findings reveal the significant role of PIEZO1 in promoting keratinocyte dysfunction, inflammation, and T cell-mediated immunopathology in psoriasis." (PMID 40495117, 2025). "Collectively, these results indicate a prominent elevation in PIEZO1 expression in the epidermal basal layer of psoriatic skin, suggesting its potential contribution to the pathophysiology of psoriasis." (PMID 40495117, 2025). "In the IMQ-induced psoriasis mouse model, IHC analysis revealed an elevation in PIEZO1 expression compared to control samples." (PMID 40495117, 2025). "In vivo, PIEZO1 KO mice showed attenuated psoriasis-like symptoms, reduced keratinocyte proliferation, inflammatory cell infiltration, and less Th17 cells compared to wild-type mice." (PMID 40495117, 2025). "To elucidate the mechanistic role of PIEZO1 in psoriasis, we harvested skin tissue samples from psoriatic patients and healthy individuals, processing them for subsequent analyses." (PMID 40495117, 2025). "This reinforces the well-established significance of the pathway in psoriasis pathogenesis and reveals a novel role for PIEZO1 as a contributor within this signaling cascade." (PMID 40495117, 2025). "This outcome is particularly significant in terms of translational potential; it prompts further exploration within the scientific community into utilizing PIEZO1 antagonists or modulators as potential therapeutic agents for psoriasis." (PMID 40495117, 2025). "Collectively, these findings substantiate the proposition that the ablation of PIEZO1 mitigates the pathogenesis of psoriasis by reducing keratinocyte proliferation and curtailing the associated inflammatory response." (PMID 40495117, 2025). "The interplay between PIEZO1 and the NF-kB/IL-17 pathway depicted in this study expands upon existing knowledge, elucidating how PIEZO1 may modulate the inflammatory state in psoriasis." (PMID 40495117, 2025). "Furthermore, PIEZO1 facilitated keratinocyte-mediated CD4 + T cell differentiation into Th17 cells, a key pathogenic factor in psoriasis." (PMID 40495117, 2025).
psoriasis (continued). "Our findings reveal that PIEZO1 modulates keratinocyte proliferation, immune cell infiltration, and T cell differentiation through the NF-kB signaling pathway, contributing to the complex pathophysiology of psoriasis." (PMID 40495117, 2025). "This study highlights the critical role of PIEZO1 in psoriatic skin inflammation and suggests that PIEZO1 may serve as a novel therapeutic target for psoriasis treatment." (PMID 40495117, 2025). "However, the specific contributions of PIEZO1 to the pathophysiology of psoriasis remain to be clarified." (PMID 40495117, 2025). "Conversely, PIEZO1 inhibition or knockdown diminishes NF-κB activation, dampens chemokine secretion, and curtails Th17 cell differentiation, highlighting PIEZO1 as a prospective therapeutic target in psoriasis." (PMID 40495117, 2025). "Even earlier, it was shown that in psoriasis, another autoinflammatory disease, healing takes more time with Piezo1 than without it." (PMID 37108693, 2023). "Importantly, PIEZO1 KO mice subjected to IMQ treatment exhibited a notable reduction in this upsurge of Th17 cells compared to WT IMQ mice, suggesting that the absence of PIEZO1 hinders Th17 cell proliferation and alleviates the emergence of psoriasis-like lesions." (PMID 40495117, 2025).
triple-negative breast carcinoma (3 papers, 2024 to 2026). An invasive breast carcinoma which is negative for expression of estrogen receptor (ER), progesterone receptor (PR), and human epidermal growth factor receptor 2 (HER2). "While optimal PIEZO1 activity is required for sustained proliferation and migratory capacity, loss of PIEZO1 conferred a survival advantage in triple-negative breast cancer cells under mechanically challenging conditions similar to those encountered in circulation." (PMID 42268805, 2026).
abdominal aortic aneurysm (2 papers, 2024 to 2025). Enlargement and ballooning of the vessel that supplies arterial blood to the abdomen, pelvis and legs. "They found that the Piezo1 inhibitor GsMTx4 could reduce the incidence of abdominal aortic aneurysm due to decreased activity of Piezo1 in VSMCs by inhibiting the mechanically solid‐like state of VSMCs." (PMID 41457305, 2025).
acute myeloid leukemia (2 papers, 2024 to 2026). Acute myeloid leukemia (AML) is a group of neoplasms arising from precursor cells committed to the myeloid cell-line differentiation. "Here, the mechanosensor PIEZO1 as a key factor in promoting acute myeloid leukemia progression and maintaining LSC stemness by HIF1A-SLC7A11 axis-mediated ferroptosis defense is uncovered." (PMID 42107071, 2026).
amyloid (2 papers, 2018 to 2024). "Taken together, we report that aging and peripheral infection augment amyloid plaque-induced upregulation of mechanoresponsive ion channels, such as Piezo1, in astrocytes." (PMID 30405400, 2018). "Future studies will focus on the signaling cascades triggered by Piezo1-mediated currents in reactive astrocytes and Piezo1 as a potential therapeutic target for amyloid plaque-induced neurodegeneration in AD." (PMID 30405400, 2018). "Utilizing the TgF344-AD rat model, we show here that Piezo1 protein expression increases in several key brain structures in response to aging, peripheral infection and amyloid plaque pathology." (PMID 30405400, 2018). "Taken together, both aging and amyloid plaque pathology trigger increases in Piezo1 channel expression, particularly in the prefrontal cortex, of TgF344-AD rats." (PMID 30405400, 2018). "Here, we utilized an aging transgenic rat model of AD (TgF344-AD) to study expression of mechanosensing Piezo1 ion channels in amyloid plaque-reactive astrocytes." (PMID 30405400, 2018). "Therefore, our aim here was to investigate cellular expression of mechanosensitive Piezo1 channels in response to amyloid plaque pathology in an aging rat model of AD." (PMID 30405400, 2018). "Increased Ca2+ activity in microglial cells exposed to Aβ may be due to Aβ-evoked UTP/UDP release by stressed neurons acting on microglial metabotropic P2Y6 receptors or Aβ-mediated mechanotransduction mediated via PIEZO1 Ca2+-permeable ion channels involved in amyloid clearance." (PMID 37966547, 2024). "To assess the relationship between Piezo1 expression and amyloid plaque pathology in adult and aged rats with and without repeated peripheral infections, we correlated Piezo1 fluorescence intensity with both GFAP and Aβ1-42 expression in the dentate gyrus of all groups." (PMID 30405400, 2018). "Interestingly, however, there were no further significant increases in hippocampal Piezo1 expression in TG rats from 12 to 18 months of age, suggesting that amyloid deposition and plaque load begin in the hippocampus before spreading further to cortical regions." (PMID 30405400, 2018).
Arthritis (2 papers, 2025 to 2026). Inflammation of a joint. "Finally, the role of Piezo1 in immune regulation was further assessed in proteoglycan-induced arthritis (PGIA) model using GsMTx4, a Piezo1 inhibitor." (PMID 41507149, 2026).
autoimmune conditions (2 papers, 2020 to 2023). "On the contrary, Piezo1 downregulation in activated LCs could result in a functional imbalance in the Th17/Treg ratio, contributing to autoimmunity and DE progress in RA, since it is known that Piezo1 loss leads to increased Treg numbers." (PMID 37108693, 2023).
beta thalassemia (2 papers, 2017 to 2023). Beta-thalassemia (BT) is characterized by deficiency (Beta+) or absence (Beta0) of synthesis of the beta globin chains of hemoglobin (Hb). "Indeed, in beta-thalassemia trait subjects, RBCs have decreased Piezo1 levels and increased contents of NMIIA but, at the same time, increased intracellular Ca2+ and decreased echinocytes." (PMID 38254651, 2023).
bladder overactivity (2 papers, 2021 to 2025). "PIEZO1 activation-induced increases in Ca2+ activity and the subsequent release of ATP onto nerve terminals and may be one explanation for the contribution of PIEZO1 signaling in bladder overactivity." (PMID 35295484, 2021). "Additionally, the lack of available and specific PIEZO1 inhibitors makes studying PIEZO1 functional contributions to overactive bladder in rats challenging." (PMID 35295484, 2021).
brain cancer (2 papers, 2025 to 2026). A primary or metastatic malignant neoplasm affecting the brain. "The fast-paced, confined growth of GBM means that brain cancer cells are under constant mechanical forces (including shear stress, compression, and tension) that activate Piezo1." (PMID 40527011, 2025). "However, only limited studies have explored the effect of FUS on brain cancer cells, and the effects of FUS on Piezo1 in brain cancer cells have not yet been investigated." (PMID 40527011, 2025).
calcific aortic valve disease (2 papers, 2025). "For instance, in calcific aortic valve disease, mechanical stress sensed through the Piezo1 ion channel promotes glutaminolysis and acetyl-CoA production, enhancing H3K27 acetylation at osteogenic genes mediated by RUNX2 in valve interstitial cells." (PMID 40511385, 2025). "In aortic valves of patients with calcific aortic valve disease, there was upregulated PIEZO1 mRNA and PIEZO1 protein with no change in PIEZO2 mRNA." (PMID 40721314, 2025).
cardiac ischemia (2 papers, 2025 to 2026). "Therefore, PIEZO1 may be a factor promoting coronary artery atheroma, which is the major cause of cardiac ischemia." (PMID 40721314, 2025). "Effects of this type might be relevant to the heart because of PIEZO1’s role in pericardial effusion, and the suggestion that lymphatic stimulators may accelerate the clearance of damage products and unwanted inflammatory mediators after cardiac ischemia." (PMID 40721314, 2025).
cognitive decline (2 papers, 2024). "Piezo1-deficient microglia lead to worsening Aβ pathology and cognitive decline." (PMID 39539343, 2024).